FOXM1 (forkhead box M1)
Diseases named in the same sentence as FOXM1 in open-access papers (continued):
Sharing a sentence is not in itself a finding about the gene and the disease.
breast cancer (continued). "Conversely, the ubiquitination E3-ligase RNF168 has been shown to cooperate with another E3 ubiquitin-protein ligase RNF8 to mediate FOXM1 ubiquitination and degradation in breast cancer response to epirubicin treatment." (PMID 29180117, 2018). "Another dataset with 593 samples that derived from the Cancer Genome Atlas (TCGA) database showed that FoxM1 transcripts were 5.213-fold elevated in breast cancer samples as compared with normal tissues." (PMID 29416660, 2018). "Among those Yin pathways, the cell cycle related pathways are dominant in all types of breast cancers, including the FOXM1 pathway that interacts with cell cycle S, G2, and M phases, but are more significant in TNBC type than other types." (PMID 29301506, 2018). "The overexpression of FoxM1 has been observed in a broad range of human cancer biopsies including breast cancer, colorectal cancer and prostate cancer, suggesting that FoxM1 is essential for caner proliferation and carcinogenesis." (PMID 30416986, 2018). "Paclitaxel has been shown to downregulate FOXM1 to mediate mitotic catastrophe and breast cancer paclitaxel sensitivity." (PMID 29180117, 2018). "FOXM1 has been shown to be an important factor in breast cancer CSC phenotype and TNBC/basal BC biology." (PMID 30572639, 2018). "More interestingly, elevated FoxM1 expression predicted poor survival in breast cancer patients, especially in the ER (+), progesterone receptor (PR) (+) subgroups and BC patients received adjuvant chemotherapy only or treated with tamoxifen only." (PMID 29416660, 2018). "Our analysis also indicated that elevated FoxM1 expression predicted worse survival in breast cancer patients with adjuvant chemotherapy only, particularly in the ER-positive subgroup." (PMID 29416660, 2018). "Elevated expression of FoxM1 in breast cancer correlates with an undifferentiated tumor phenotype and a negative clinical outcome." (PMID 29416660, 2018). "Silencing of FOXM1 by RNAi also abolished estrogen-stimulated breast cancer cell proliferation and overcame acquired tamoxifen resistance." (PMID 30360388, 2018). "There is increasing awareness that development of FoxM1 inhibitor is a promising strategy for breast cancer therapy." (PMID 29416660, 2018). "In this study, we explored the prevalence and clinical implication of FoxM1 overexpression in Saudi breast cancer." (PMID 29707121, 2018). "In concordance, overexpression of FOXM1 can enhance the resistance of breast cancer cells to paclitaxel and is a poor prognostic factor in breast cancer patients." (PMID 29180117, 2018). "In breast cancer, FoxM1 was the downstream target of HER2, then contributes to the pathogenesis of breast cancer." (PMID 29554906, 2018). "For example, the expression of FoxM1 in different breast cancer subtypes, as our data showed, was correlated to different expression patterns across different breast cancer subtypes." (PMID 29416660, 2018). "In general, FOXM1 protein level is higher in epirubicin resistant cells compared to sensitive breast cancer cells." (PMID 29180117, 2018). "Recently, it was identified that FoxM1 acts as a critical regulator of mammary differentiation with significant implications for the development of aggressive breast cancers." (PMID 29416660, 2018). "This indicates that an intimate functional relationship between FOXM1 and ERα in breast cancer development and probably, endocrine therapy sensitivity." (PMID 29180117, 2018). "Khongkow and colleagues reported that paclitaxel targets FoxM1 to regulate KIF20A in mitotic catastrophe and dysfunction of FoxM1 expression will lead to breast cancer paclitaxel resistance." (PMID 29416660, 2018). "Paclitaxel can also downregulate FOXM1 to mediate mitotic catastrophe and senescence in breast cancer cells." (PMID 29180117, 2018). "In order to identify these molecular targets, we analyzed a large cohort of breast cancer cases and found that FoxM1 was over-expressed in 79% of all BC studied." (PMID 29707121, 2018).
breast cancer (continued). "In a dataset from Richardson’s study, FoxM1 was 17.629-fold elevated in breast cancer samples as compared with normal tissues (p = 1.73e-9)." (PMID 29416660, 2018). "Myriad of studies have demonstrated that FoxM1 overexpressed in multiple cancers types, including breast cancer." (PMID 29416660, 2018). "Our data is in concordance with these finding as we found a significant association between FoxM1 overexpression and VEGF and MMP-9 in our cohort of breast cancer cases." (PMID 29707121, 2018). "A recent study demonstrated that casticin treatment induced apoptosis in breast cancer cells via the activation of forkhead box O3 (FOXO3a) and the repression of forkhead box protein M1 (FOXM1)." (PMID 30401729, 2018). "More interestingly, accumulating evidences indicated that FoxM1 was significantly involved in drug resistance that compromised the efficacy of transtuzumab, tamoxifen and taxanes in the treatment of breast cancer." (PMID 29416660, 2018). "In breast cancer treated with epirubicin, FOXM1 is modified through SUMOylation, which leads to its ubiquitination and degradation by RNF168 E3 ubiquitin ligase." (PMID 30208972, 2018). "Previous studies have shown the expression and the prognostic significance of FoxM1 in several types of cancer including breast cancer." (PMID 29707121, 2018). "It has been shown that FOXM1 is SUMOylated in breast cancer cells in response to treatment with epirubicin and mitotic inhibitors, including paclitaxel." (PMID 29180117, 2018). "These evidences suggest that FoxM1 is an attractive prognostic prediction biomarker and promising therapeutic target for breast cancer." (PMID 29416660, 2018). "FoxM1 alone is a major predictor of adverse outcome in several carcinomas, including carcinoma of the breast, ovary, lung, liver, and stomach." (PMID 29789556, 2018). "Recently, Inoguchi and his colleagues showed that downregulation of miR-24-1 in breast cancer cells leads to FOXM1 overexpression and promotes aggressive cancer behavior via regulation of p27kip1 degradation." (PMID 27999212, 2017). "Here we demonstrated that FOXM1 was differentially expressed between MIBC subtypes concordant to its subtype specific expression in breast cancer." (PMID 28498805, 2017). "A recent study showed that the FOXM1 cistrome is a powerful index to predict breast cancer outcomes." (PMID 28666461, 2017). "We previously reported that FoxM1 is a critical mediator of IGF-1R-stimulated invasion in breast cancer cells." (PMID 29212236, 2017). "Since FOXM1 target genes have been identified in 8 cell lines, we inferred FOXM1 activities in breast cancer samples using target genes identified in each individual cell line, resulting in eight iRASs for a tumor sample." (PMID 29100329, 2017). "Together with the ChIP data, this indicates that at least six out of 15 investigated mitotic kinesins are direct targets of MMB and of FOXM1 in breast cancer cells." (PMID 28061449, 2017). "That function of the FoxM1/Rb complex in breast cancer cells would inhibit differentiation and support poorly differentiated tumor phenotype." (PMID 28387346, 2017). "For instance, FOXM1 confers resistance to paclitaxel by altering microtubule dynamics via promoting Stathmin expression in breast cancer." (PMID 28051999, 2017). "FoxM1 is known to be up-regulated in the majority of solid human cancers, including TNBC breast cancer, and is implicated in invasion and metastasis." (PMID 29312532, 2017). "We demonstrate that six mitotic kinesins and two microtubule-associated non-motor proteins (MAPs) CEP55 and PRC1 are direct transcriptional targets of MuvB, B-MYB and FOXM1 in breast cancer cells." (PMID 28061449, 2017). "And moreover, in human breast cancer, miRNA-211 directly inhibit CDC25B expression in breast cancer cells, alters other related target proteins CCNB1 and FOXM1, and then inhibits breast cancer cells growth, migration, and invasion and lead G2/M arrest." (PMID 28924391, 2017).
breast cancer (continued). "The six kinesins and two MAPs regulated by MMB and FOXM1 are expressed at higher levels in breast cancer cell lines compared to control cell lines." (PMID 28061449, 2017). "An increasing number of studies have reported that FoxM1 mediates drug resistance in many types of cancers, including gastric cancer, breast cancer and glioblastoma, by regulating the expression of downstream targets." (PMID 28148279, 2017). "To validate this finding further, we next studied the expressions of AURKA and FOXM1 in primary human breast cancer samples." (PMID 28114286, 2017). "Next, immunohistochemistry was used to determine protein levels of AURKA and FOXM1 in 269 primary human breast cancer patient samples from Sun Yat-Sen University Cancer Center." (PMID 28114286, 2017). "In breast cancers, FoxM1 has been shown to form a positive feedback loop with the PDGF/Akt signaling pathways." (PMID 28387346, 2017). "Consistently, breast cancer patient samples portrayed a strong and significant correlation between the expression levels of FOXM1 and AURKA." (PMID 28114286, 2017). "We found that FOXM1 is overexpressed in paclitaxel-resistant MCF-7 TaxR breast cancer cell lines when compared with the parental sensitive MCF-7 cells." (PMID 25961928, 2016). "Aberrant expression of FoxM1 is involved in several tumor types, including hepatocellular carcinoma, basal cell carcinoma, breast cancer, lung cancer, prostate cancer, glioblastomas, and gastric cancer, suggesting its oncogenic role in carcinogenesis." (PMID 27086911, 2016). "A thiazole ring containing thiostrepton, an antibiotic with antitumor activities, was shown to induce arrest and death of breast cancer cells through downregulating FOXM1 expression." (PMID 26942015, 2016). "The key network routers and high impact genes that contribute flows to FOXM1 in each breast cancer context also differ." (PMID 26975659, 2016). "FoxM1 is subject to SUMOylation at lysine 463 and this posttranslational modification is required for the full repression of miR-200b/c in breast cancer cells." (PMID 26905733, 2016). "Overexpression of microRNA miR802 led to downregulation of FOXM1 and inhibited proliferation of breast cancer cells." (PMID 26942015, 2016). "Collectively, these data suggest that OTUB1 limits the ubiquitination and degradation of FOXM1 in breast cancer and has a key role in genotoxic agent resistance." (PMID 26148240, 2016). "Our results indicate that FOXM1 regulates ERK signaling in breast cancer cells and support previous findings suggesting that FOXM1 is one of the major upstream effectors of ERK signaling in human hepatocellular carcinoma." (PMID 26918606, 2016). "Forkhead box protein M1 (FOXM1) in contrast was a key regulator of EMT in breast cancer, as it binds and stimulates the promotor of Slug, which is responsible for EMT-promotion." (PMID 27529216, 2016). "We also examined an Akt-signaling pathway in SCLC cells since the PI3K/AKT/mTOR pathway is frequently activated in SCLC tumors and exogenous introduction of FOXM1 activates the AKT pathway in breast cancer cells." (PMID 26871945, 2016). "It has been reported that ERβ represses FOXM1 expression in breast cancer cells primarily through competing with ERα on binding to the ERE element in the FOXM1 promoter." (PMID 26885609, 2016). "Collectively, these data suggest that RNF168 cooperates with RNF8 to mediate the ubiquitination and degradation of SUMOylated FOXM1 in breast cancer genotoxic response." (PMID 27526106, 2016). "The forkhead box M1 (FOXM1) transcription factor has a central role in genotoxic agent response in breast cancer." (PMID 27526106, 2016).
breast cancer (continued). "Treatment of breast cancer cells with adenoviral vector expressing short hairpin downregulating FOXM1 led to inhibition of breast cancer tumor formation." (PMID 26942015, 2016). "Their investigations showed that ERβ had an antiproliferative effect through repression of FOXM1 expression in breast cancer cells; this effect was mediated by an estrogen-response element within the proximal promoter region that is also a target of ERα." (PMID 26942015, 2016). "Their results showed that FOXM1 is a physiologic regulator of ERα expression in breast cancer cells, both at the protein and at mRNA levels." (PMID 26942015, 2016). "The nuclear factor NF-kappa-B1 (NFκB1) interacted with FOXM1 in the presence of doxorubicin to protect breast cancer cells from DNA damage." (PMID 26942015, 2016). "To validate the computational predictions and the biological effects of miR-671-5p targeting FOXM1, we first examined the expression of miR-671-5p and FOXM1 in breast cancer cell lines." (PMID 26588055, 2016). "FOXM1 is a downstream target of 14-3-3ζ, a marker of endocrine therapy resistance in breast cancer malignancy." (PMID 26942015, 2016). "Once FOXM1 targeted agents are available, appropriate clinical testing in different breast cancer subtypes is warranted, most likely in a biomarker-driven setting." (PMID 26942015, 2016). "Our results indicate that the FOXM1 plays an important role in breast cancer progression by transcriptionally regulating eEF2-Kinase expression which is an equally important and an emerging target in TNBC and other solid tumors." (PMID 26918606, 2016). "In the present study, knockdown of FOXM1 led to a marked reduction in cyclin D1 expression, which was recently shown to be regulated by eEF2K in breast cancer cells." (PMID 26918606, 2016). "We found that miR-671-5p overexpression resulted in downregulated FOXM1, and further demonstrated miR-671-5p can sensitize breast cancer to anticancer drugs." (PMID 26588055, 2016). "Other investigators reported that the interruption of FOXM1 expression in breast cancer cells sensitized the cells to DOX." (PMID 27439614, 2016). "Given the important roles of FOXM1, EPHA4 and EPHA7 on breast cancer outcome, FOXM1 and miR-135a were good candidates for a siRNA knockdown study." (PMID 27528030, 2016). "Together these results suggest that FOXM1 regulates KIF20A to modulate paclitaxel sensitivity in breast cancer." (PMID 25961928, 2016). "Forced expression of miR-671-5p in breast cancer cell lines downregulated FOXM1 expression, and attenuated the proliferation and invasion in breast cancer cell lines." (PMID 26588055, 2016). "Attenuation of FOXM1 expression by RNA interference or alternative reading frame derived peptide inhibitors increased the therapeutic sensitivity of breast cancer to paclitaxel." (PMID 27074562, 2016). "Our immunohistochemical and statistical analysis of breast cancer patient samples shows that there is a significant and strong correlation between FOXM1 and KIF20A expression, further confirming the regulation of KIF20A by FOXM1 in vivo." (PMID 25961928, 2016). "FOXM1 can mediate drug sensitivity or resistance, and in breast cancer FOXM1 overexpression confers resistance to trastuzumab and paclitaxel." (PMID 27074562, 2016). "Key transcriptional regulators that had been implicated in breast cancer pathogenesis such as RB1, FOXM1 and E2F1 are key targets within our model and the high values of flow differences further highlight their importance in breast cancer." (PMID 26975659, 2016). "In this study, we examined the potential role of OTUB1 in the regulation of FOXM1 expression in genotoxic drug-sensitive and -resistant breast cancer cells." (PMID 26148240, 2016). "For example, 14-3-3ζ was found to interact with ErbB2 to regulate several important metastasis mediators including E-cadherin, fork head box protein M1 (FOXM1) and β-catenin, such as to promote breast cancer metastasis." (PMID 26730736, 2016).
breast cancer (continued). "Although the mechanism of FoxM1 and OGlcNAcylation is poorly characterized, sentinel studies suggest that hyper O-GlcNAcylation of FoxM1 mediators in breast cancer prevent the degradation of FoxM1, to promote transformation of cells in breast cancer." (PMID 27703839, 2016). "Down-regulation of FOXM1 resulted in a significant increase in the number of apoptotic MDA-MB-231 cells (p < 0.01), suggesting that expression of FOXM1 promotes cell survival and prevents apoptotic cell death in breast cancer cells." (PMID 26918606, 2016). "Nevertheless, it also seems to be of importance in several cancer types: It is supposed to suppress breast cancer proliferation by targeting and suppressing FoxM1 and showed a moderate tumor suppressive activity in liver cancer cells." (PMID 27092493, 2016). "Together, these results suggest that RNF168 can modulate the turnover of FOXM1 in untreated breast cancer cells and in response to epirubicin." (PMID 27526106, 2016). "The physiological relevance of the regulation of FOXM1 by OTUB1 is underscored by the strong and significant association between FOXM1 and OTUB1 in breast cancer patient samples." (PMID 26148240, 2016). "Our results demonstrate that miR-671-5p plays an important role in DNA repair by targeting FOXM1, which enhances the sensitivity of anticancer drugs in breast cancer cells." (PMID 26588055, 2016). "FOXM1 has been shown to play a critical role in development of resistance to breast cancer therapeutics." (PMID 26942015, 2016). "Recent experiments showed that it can induce apoptosis of breast cancer cells by reducing the expression of FOXM1." (PMID 26942015, 2016). "To explore this possibility, we first overexpressed RNF168 and two other DDR-related E3-ligases, RNF4 and RNF8, in the MCF-7 breast carcinoma cells, and studied their effects on FOXM1 expression." (PMID 27526106, 2016). "We next determined the role of FoxM1 in the proliferation of breast cancer cells through the PDGF-A/AKT pathway." (PMID 25869208, 2015). "We then assessed the effect of altering FoxM1 on the activity of the PDGF-A promoter in breast cancer cells." (PMID 25869208, 2015). "FoxM1 expression levels were elevated in 87% of breast cancer patients and the elevated FoxM1 levels were correlated with breast cancer development." (PMID 25869208, 2015). "Both SNPs are located directly under the binding sites for a number of breast cancer-relevant transcription factors, including forkhead box M1 (FOXM1) and GATA binding protein 3 (GATA3)." (PMID 25652398, 2015). "Aberrant expression of FoxM1 has been observed in the majority of human solid human tumors, including breast cancer." (PMID 25869208, 2015). "Moreover, several therapeutic targets for breast cancer, such as human epidermal growth factor receptor 2 and estrogen receptor alpha, may regulate the expression of FoxM1, which underlines the importance of FoxM1 as a therapeutic target in breast cancer treatment." (PMID 25869208, 2015). "Overall, greater than fifty FOXM1 targets (related to mitochondria, glycolysis, the EMT, and protein synthesis) that we identified in MCF7-FOXM1 cells were also transcriptionally elevated in human breast cancer cells in vivo." (PMID 26087310, 2015). "Increased FoxM1 resulted in the upregulation of PDGF-A, which led to activation of the AKT pathway and increased breast cancer cell proliferation and tumorigenesis, whereas knockdown of FoxM1 does the opposite." (PMID 25869208, 2015). "It has been demonstrated that DACH1 antagonizes FOXM1 signaling through competitively binding to the conserved forkhead specific DNA sequence in breast cancer." (PMID 25788272, 2015). "Knockdown of PDGF-A or blockade of AKT activation inhibited the expression of FoxM1 in breast cancer cells." (PMID 25869208, 2015). "Enhanced expression of FoxM1 in breast cancer cells increased invasion and metastasis of these cells and increased acquired drug resistance as well." (PMID 25869208, 2015).